NANOG (Nanog homeobox)
Diseases named in the same sentence as NANOG in open-access papers (continued):
Sharing a sentence is not in itself a finding about the gene and the disease.
diabetes (3 papers, 2012 to 2024). "Importantly, no upregulation of progenitor markers, such as neurogenin 3 (NEUROG3), POU class 5 homeobox 1 (POU5F1), and nanog homeobox (NANOG) was found in T2D β-cells, in contrast to what was previously reported in diabetes mouse models." (PMID 38731945, 2024). "Immunocytochemistry further validated robust expression of diverse pluripotency markers, including SSEA-4, TRA-1-60, TRA-1-81, OCT4, SOX2, KLF4 and NANOG in HK-derived iPS clones regardless of patient age and status of diabetes." (PMID 22308265, 2012).
epithelial dysplasia (3 papers, 2014 to 2026). "Immunohistochemistry (IHC) was used to identify stem cell biomarkers in tissue samples, most studies demonstrated that higher expression of stem cell markers (CD44, ALDH1, HELLS, TARIF, SOX2, NANOG, and CD147) correlated with severity of epithelial dysplasia." (PMID 41778103, 2026). "However, only a few studies are found in the literature that compare NANOG expression in OSCC and epithelial dysplasia." (PMID 38558704, 2024).
esophageal adenocarcinoma (3 papers, 2020 to 2024). A malignant tumor with glandular differentiation arising predominantly from Barrett mucosa in the lower third of the esophagus. "Expression of NANOG in pre-treatment biopsies is associated with poor response to neoadjuvant chemoradiation, recurrence, and median overall survival in patients with esophageal adenocarcinoma." (PMID 38760583, 2024). "Positive NANOG expression showed to be a significant risk factor for poorer overall survival in esophageal adenocarcinoma (HR = 1.40, 95% CI = 1.09–1.80, p = 0.006)." (PMID 37461005, 2023). "Mechanistic experiments should elucidate the pathomechanism of NANOG as well as the stem-like biological properties and their influence on (radio-) chemoresistance as well as patient survival in esophageal adenocarcinoma." (PMID 37461005, 2023). "In this study, 660 esophageal adenocarcinoma samples were evaluated regarding their NANOG expression and its possible influence on clinicopathologic characteristics and overall survival." (PMID 37461005, 2023). "This study aims to elucidate the role of NANOG in esophageal adenocarcinoma." (PMID 37461005, 2023). "However, further research is needed to evaluate the impact of neoadjuvant treatment on NANOG expression in esophageal adenocarcinoma—especially dependent on the difference between chemotherapy versus chemoradiotherapy." (PMID 37461005, 2023).
esophageal squamous cell carcinoma (3 papers, 2015 to 2023). Esophageal squamous cell carcinoma (ESCC) is a type of esophageal carcinoma (EC) that can affect any part of the esophagus, but is usually located in the upper or middle third. "Immunohistochemical analyses of NANOG expression in 115 patients suffering from esophageal squamous cell carcinomas and 19 patients suffering from adenocarcinomas showed that positive NANOG expression correlated significantly with worse survival." (PMID 37461005, 2023). "NANOG promoted proliferation and invasion in esophageal squamous cell carcinoma cell lines." (PMID 37461005, 2023). "To further extend these findings, we show that NANOG regulates the expression of EMT mediators in primary mouse keratinocytes, in immortalized human keratinocytes (HaCat), and in human esophageal SCC cells (TE2)." (PMID 25988972, 2015).
invasive carcinoma (3 papers, 2019 to 2020). A carcinoma that is not confined to the epithelium, and has spread to the surrounding stroma. "In oral dysplasia, NANOG protein expression was significantly correlated with higher risk of progression to invasive carcinoma and higher cancer incidence with a stronger cytoplasmic reaction." (PMID 33643897, 2020). "Cytoplasmic and nuclear NANOG expression was detected early in oral epithelial dysplasias while being absent in normal adjacent epithelia, and positive NANOG expression in oral dysplasias was significantly correlated with a higher risk of progression to invasive carcinoma." (PMID 31484317, 2019). "This is probably why analysis of NANOG in TANT showed highly variable values, from undetectable expression to high expression similar to invasive carcinoma." (PMID 32733958, 2020).
medulloblastoma (3 papers, 2013 to 2016). A malignant, invasive embryonal neoplasm arising from the cerebellum. "Therefore, we predicted that OCT4 itself is capable of reprogramming the DAOY medulloblastoma cells via a network leading to the expression of OCT4, SOX2, and NANOG." (PMID 24202329, 2013).
meningioma (3 papers, 2018 to 2019). A generally slow growing tumor attached to the dura mater. "A recent immunohistochemical survey in GI meningiomas identified a number of SC markers, including OCT4, NANOG, SOX2, KLF4, and c-MYC, on microvessels that led to the suggestion that these vessels may be associated with meningioma initiation." (PMID 31083655, 2019). "These techniques made it possible to support the research theory that an overexpression of NANOG and other markers of pluripotency and stemness in meningiomas, such as SOX2 and OCT4, could be exploited to target potentially pluripotent "stem cell-like" cells." (PMID 29495368, 2018).
myeloma (3 papers, 2015 to 2022). "Additional regulators of NANOG in myeloma are Hh and Wnt, two “stemness” pathways that are governed, at least in part, by BTK." (PMID 26415231, 2015). "Based on our data, overexpression of BTK leads to increased levels of NANOG in myeloma cells." (PMID 26415231, 2015). "Although many details have yet to be filled in, it is possible that NANOG-dependent myeloma stemness may be therapeutically targeted using small-molecule BTK inhibitors, such as ibrutinib." (PMID 26415231, 2015). "Our most recent, unpublished work indicates that up-regulation of BTK in myeloma cells leads to phosphorylation and activation of STAT3, a crucial regulator of NANOG." (PMID 26415231, 2015). "Therefore, in this study, we only demonstrated that ALKBH5 increased the percentage of SP cells and CD138-/CD34- myeloma stem cells by activating cancer stem cell related HIPPO pathway signalling and promoting the expression of pluripotency factors NANOG, SOX2 and OCT4." (PMID 35414790, 2022).
ovarian tumor (3 papers, 2016 to 2022). "Additionally, FOXK2 knockdown significantly reduced mRNA expression levels of stemness-associated TFs (SOX2, OCT4, and NANOG) and stemness marker ALDH1A1 in OC cell lines and primary cells dissociated from a human ovarian tumor." (PMID 35349489, 2022).
prostate adenocarcinoma (3 papers, 2016 to 2024). "HMGB3 cooperates with SOX9 to induce NANOG transactivation, promote the expression of oncogenic genes downstream of NANOG, and further enhance prostate adenocarcinoma cell survival and migration." (PMID 37328851, 2023). "Thus, HMGB3/SOX9-mediated NANOG induction may lead to increased viability of prostate adenocarcinoma cells." (PMID 39062899, 2024). "Recently, a new mechanism for regulating the development of prostate adenocarcinoma (PCa), which involves the deregulation of SOX9, HMGB3, and NANOG, was discovered." (PMID 39062899, 2024).
renal cell carcinoma (3 papers, 2018 to 2023). "A high expression of NANOG and OCT4 in renal cell carcinomas has been associated with poor patient survival, highlighting the importance of targeting these genes to improve patient outcomes." (PMID 37372456, 2023). "This study was conducted to evaluate the expression patterns and clinical significance of octamer-binding transcription factor 4 (OCT4) and NANOG as the key stem cell factors in renal cell carcinoma (RCC)." (PMID 30082842, 2018). "A significant association was found among nuclear coexpression of OCT4 and NANOG, worse PFS in RCC, and the clear cell renal cell carcinomas (ccRCC) subtype." (PMID 30082842, 2018).
rhabdomyosarcoma (3 papers, 2014 to 2020). A rare aggressive malignant mesenchymal neoplasm arising from skeletal muscle. "During our ongoing study on rhabdomyosarcoma, we unexpectedly noticed an atypical cytoplasmic localization of NANOG, which resembled the perinuclear localization of centrosomes." (PMID 32168958, 2020). "During our ongoing study aimed at the analysis of established and patient-derived rhabdomyosarcoma cell lines, we revealed an intriguing extranuclear localization of NANOG protein." (PMID 32168958, 2020). "In this study, we isolated rhabdomyosarcoma CSC with stem-like features (high expression of NANOG and OCT3/4, self-renewal ability, multipotency)." (PMID 25329465, 2014).
testicular cancer (3 papers, 2011 to 2024). A primary or metastatic malignant neoplasm that affects the testis. "In this study, we analysed NANOG-regulated miRNAs to determine their role as prominent epigenetic regulators of pluripotency in testicular cancer." (PMID 38693576, 2024). "For example, SOX2, NANOG and LIN28 expression can be used to distinguish different histological subtypes of human testicular cancers." (PMID 21851623, 2011). "Higher expression of NANOG is concerned with poor prognosis for testicular cancer, colorectal cancer, gastric cancer, non-small cell lung carcinoma, ovarian cancer, and liver cancer." (PMID 32493501, 2020).
uveal melanoma (3 papers, 2013 to 2020). A melanoma derived from melanocytes of the uveal tract. "In addition, we saw consistent up-regulation of the stem cell factor NANOG in BAP1-depleted uveal melanoma cells." (PMID 23915344, 2013).
viral infection (3 papers, 2015 to 2025). "On day 14 after viral infection, RT-qPCR analysis showed that the expression levels of endogenous NANOG, OCT4, and SOX2 were increased in H9-OCT4pGFPdF populations co-expressing OSKM and circBIRC6 (OSKMB) or circCORO1C (OSKMC) compared with H9-OCT4pGFPdFs expressing only OSKM." (PMID 29074849, 2017).
adenomyosis (2 papers, 2015 to 2017). The growth of endometrial tissue inside the muscular wall of the uterine corpus. "Whereas, mRNA expression of NANOG, OCT4 and SOX2 in cultured uterine myometrial cells isolated from cows with adenomyosis was increased compared to those isolated from normal uteri (P < 0.05)." (PMID 26416515, 2015). "Protein expression of NANOG and SOX2 was significantly decreased in stromal cells isolated from uteri with adenomyosis compared to those obtained from normal uteri (P < 0.05)." (PMID 26416515, 2015). "However, in stromal cells protein expression of NANOG and SOX2 was significantly decreased in the case of adenomyosis." (PMID 26416515, 2015).
cholangiocarcinoma (2 papers, 2019 to 2020). A carcinoma that arises from the intrahepatic biliary tree (intrahepatic cholangiocarcinoma) or from the junction, or adjacent to the junction, of the right and left hepatic ducts (hilar cholangiocarcinoma). "Here we also found that glucose depletion in cholangiocarcinoma organoids induced an increase in their expression of stem cell markers, including LGR5, CD44, EpCAM, NANOG and OCT4 and more pronounced stem cell phenotypic characteristics such as resistance to gemcitabine." (PMID 31835877, 2019).
chordoma (2 papers, 2009 to 2025). Chordomas are rare malignant tumors arising from embryonic remnants of the notochord in axial skeleton. "In the RAB3B‐small‐interfering RNA (siRNA)‐treated chordoma cells, mRNA and protein levels of chordoma stemness markers (TBXT, NANOG, OCT4, and SOX2) were significantly decreased." (PMID 40135815, 2025). "Based on the transcriptomic data of clinical chordoma tissues, RAB3B showed a high correlation with stemness markers, such as TBXT (R = 0.85, p = 5e–15), OCT4 (R = 0.5, p = 0.00016) and NANOG (R = 0.41, p = 0.0027)." (PMID 40135815, 2025). "To evaluate the roles of other RAB3 members in the chordoma stemness and tumorigenic functions, we found that RAB3A, RAB3C, and RAB3D regulated the proliferation of CH22 cells, whereas they did not control the expressions of stemness markers, such as TBXT, NANOG, OCT4 and SOX2." (PMID 40135815, 2025).
chronic myeloid leukemia (2 papers, 2019 to 2025). "In contrast to NANOG-mediated repression of MIR17HG in HL-60 our gene expression data have shown that AML cell line NOMO-1 shared elevated transcript levels of MIR17HG with chronic myeloid leukemia (CML) cell line K-562." (PMID 31825998, 2019).
cutaneous melanoma (2 papers, 2022 to 2024). A primary melanoma arising from atypical melanocytes in the skin. "When analyzing the H-Score for the immunohistochemical reaction with anti-NANOG antibodies in the group of patients with primary cutaneous melanoma, 30 patients presented positive results (H-Score > 0)." (PMID 39459448, 2024).
dysgerminoma (2 papers, 2007 to 2023). A malignant germ cell tumor characterized by the presence of a monotonous primitive germ cell population. "Approximately half of the dysgerminomas and gonadoblastomas expressed NANOG, whereas tumours with somatic differentiation were largely negative." (PMID 17274819, 2007).
endometrial tumors (2 papers, 2018 to 2022). "In this study, we observed that the expression of SOX2 and MYC, but not that of OCT4 and NANOG, in endometrial tumors is associated with poor histological differentiation and prognosis, suggesting the involvement of SOX2 in oncogenesis." (PMID 30510261, 2018). "Thus, in this study, we checked the association of SOX2, OCT4, NANOG, and MYC expressions with histological differentiation of endometrial tumors, and observed that the expressions of SOX2 and MYC, but not that of OCT4 and NANOG, correlate with advanced tumor grades." (PMID 30510261, 2018).
gastric adenocarcinoma (2 papers, 2020 to 2023). "Saffron extract at concentrations of 20, 40 and 100 μg/ml applied for 24, 48 and 72 hours reduced the expression self-renewal genes such as OCT4, KLF, SOX2, NANOG, and nucleostemin in gastric adenocarcinoma tumor cell line." (PMID 32711409, 2020).
Infertility (2 papers, 2021). "NANOG is required to provide wild-type numbers of PGCs and is able to confer germline specification in the absence of instructive external signals, whereas Resf1 deletion causes infertility in both male and female mice." (PMID 34607919, 2021).
leiomyoma (2 papers, 2017 to 2023). A well-circumscribed benign smooth muscle neoplasm characterized by the presence of spindle cells with cigar-shaped nuclei, interlacing fascicles, and a whorled pattern. "Many proteins such as F3, WNT2, CDH1, and LIF shown in the protein–protein interaction networks are well known in leiomyoma pathogenesis, and others, such as ICAM1, CXCL8, CCL2, and NANOG are novel and require further investigation." (PMID 36835153, 2023).
lung squamous cell carcinoma (2 papers, 2020 to 2023). "In lung squamous cell carcinoma, a good correlation between NANOG and SOX2 expression was observed; however, there was no clear correlation with survival outcome." (PMID 32635524, 2020).
malignant mesothelioma (2 papers, 2020 to 2021). A malignant neoplasm of the pleura or peritoneum, arising from mesothelial cells. "For the first time, we showed that genes and proteins of pluripotency factors NANOG and SOX2 are expressed in normal mesothelium and malignant mesothelioma." (PMID 32664372, 2020).
metastatic carcinoma (2 papers, 2019 to 2021). A carcinoma which has spread from the original site of growth to another anatomic site. "As NANOG is not expressed in most adult tissues, our findings identify NANOG as a potential therapeutic target in the treatment of NANOG-expressing metastatic cancers." (PMID 34638956, 2021). "On the other hand, various studies support the notion that NANOG is highly expressed in late-stage, poorly differentiated, and metastatic carcinomas." (PMID 31484317, 2019).
nasopharyngeal carcinoma (2 papers, 2017 to 2019). A carcinoma arising from the nasopharyngeal epithelium. "In nasopharyngeal carcinomas, cytoplasmic NANOG was particularly evident at the invasive edge of tumours compared to low cytoplasmic NANOG expression in the non-cancerous epithelium, and showed clinical relevance associated to poor prognosis." (PMID 28894270, 2017).
oral epithelial dysplasia (2 papers, 2019). "Similarly, we recently demonstrated that NANOG expression was a novel cancer risk marker using the same subset of patients with oral epithelial dysplasia." (PMID 31640140, 2019). "Similarly, we have recently reported a novel role for another pluripotency factor NANOG as a cancer risk marker using the same subset of 55 patients with oral epithelial dysplasia." (PMID 31640140, 2019). "NANOG expression was evaluated by immunohistochemistry in 55 patients with oral epithelial dysplasia, and 125 OSCC patients." (PMID 31484317, 2019). "NANOG protein expression was evaluated by immunohistochemistry in a set of 55 oral epithelial dysplasias." (PMID 31484317, 2019).
ovarian endometriosis (2 papers, 2014 to 2018). A non-neoplastic disorder characterized by the growth of endometrial tissue in the ovaries. "In this study, NANOG expression was significantly increased in the ectopic endometrium of women with ovarian endometriosis." (PMID 24884521, 2014). "In reproductive-age women with ovarian endometriosis, the transcriptional factor SOX2 and NANOG are over expression." (PMID 24884521, 2014). "SOX2, NANOG, and OCT4 protein were mainly expressed in the nuclei of glandular epithelial or stromal cells of ectopic and eutopic endometrium of ovarian endometriosis and normal control endometrium, with low expression detected in the cytoplasm of both cell types." (PMID 24884521, 2014). "SOX2 mRNA expression in the eutopic endometrium of ovarian endometriosis were significantly higher than that in normal endometrium (P = 0.02); expression of NANOG and OCT4 mRNA in eutopic endometrium increased but no statistically significant when compared with normal controls." (PMID 24884521, 2014). "We aimed to analyze the transcription pluripotency factors sex-determining region Y-box 2 (SOX2), Nanog homeobox (NANOG), and octamer-binding protein 4 (OCT4) in the endometrium of reproductive-age women with and without ovarian endometriosis." (PMID 24884521, 2014). "Therefore, we aimed to examine and compare SOX2, NANOG, and OCT4 expression in endometrial or endometriotic tissues from women with and without ovarian endometriosis." (PMID 24884521, 2014).
pancreatic ductal adenocarcinoma (2 papers, 2019 to 2025). An infiltrating adenocarcinoma that arises from the epithelial cells of the pancreas. "Furthermore, statistical analysis of DNA methylation indicated that target genes of NANOG, Polycomb-group target genes, and/or genes with an AACTTT promoter motif exhibit a methylation profile suggesting a predisposition to cancer development, such as pancreatic ductal adenocarcinoma." (PMID 40287726, 2025).
papilloma (2 papers, 2015 to 2020). A benign epithelial neoplasm that projects above the surrounding epithelial surface and consists of villous or arborescent outgrowths of fibrovascular stroma. "Spindle SCC-derived cell lines (CarB, CarC and MSC11A5) and non-spindle SCC-derived cell line (MSC11B9) expressed higher levels of NANOG, compared to cell lines derived from papillomas (PB) or transformed keratinocytes (PDV)." (PMID 25988972, 2015). "Analysis of the global transcriptional profiles of papillomas by RNA-seq indicated that, at this early stage of tumorigenesis, transgenic NANOG is already upregulating key transcriptional regulators of EMT." (PMID 25988972, 2015). "Importantly, NANOG expression was also up-regulated during the late stages of tumor progression, when papillomas become more invasive and turn into SCCs." (PMID 32197405, 2020). "We confirmed NANOG overexpression in the TG papillomas and carcinomas." (PMID 25988972, 2015). "To obtain mechanistic insight on how NANOG promotes skin tumorigenesis, we performed RNA-seq of CTR (n = 4) and TG (n = 3) papillomas." (PMID 25988972, 2015). "Also, Nanog-overexpressing papillomas upregulate miR-21, which is another key inducer of EMT26, 37 previously shown to be regulated by NANOG in cultured cells." (PMID 25988972, 2015).